LPAR3 (lysophosphatidic acid receptor 3)
Description:
Receptor for lysophosphatidic acid (LPA), a mediator of diverse cellular activities. May play a role in the development of ovarian cancer. Seems to be coupled to the G(i)/G(o) and G(q) families of heteromeric G proteins.
Synonyms: EDG7; LPA3; LP-A3; Edg-7; RP4-678I3; HOFNH30; GPCR
Tractability: Small molecule: a high-quality ligand is known; it belongs to a druggable protein family. Antibody: its Gene Ontology location is reachable by antibodies, with high confidence; UniProt places it where antibodies can reach, with medium confidence; UniProt predicts a signal peptide or a membrane-spanning region; the Human Protein Atlas places it where antibodies can reach. PROTAC: ubiquitination databases record sites on it; a small molecule that binds it is known.
Target class: EDG receptor; Family A G protein-coupled receptor; Lipid-like ligand receptor (family A GPCR); Membrane receptor; Small molecule receptor (family A GPCR)
Chemical probes: CHEMBL201482, CHEMBL202361, PD081961
Gene: Protein-coding gene on chromosome 1 (84,811,601 to 84,893,540, reverse strand). Ensembl gene ENSG00000171517.
Subcellular location: Cell membrane
Subcellular location (Human Protein Atlas): Plasma membrane; Primary cilium
Pathways (Reactome):
Signal Transduction: G alpha (i) signalling events; G alpha (q) signalling events; Lysosphingolipid and LPA receptors
Gene Ontology:
Molecular function: protein binding; G protein-coupled receptor activity; lipid binding; G-protein alpha-subunit binding; lysophosphatidic acid receptor activity; phospholipid binding
Biological process: adenylate cyclase-activating G protein-coupled receptor signaling pathway; chemical synaptic transmission; G protein-coupled receptor signaling pathway, coupled to cyclic nucleotide second messenger; positive regulation of cytosolic calcium ion concentration; G protein-coupled receptor signaling pathway; gene expression; positive regulation of calcium ion transport
Cellular component: plasma membrane; cytoplasm; axon; membrane; synapse
Genetic constraint (gnomAD): Loss-of-function variants: 7 observed, 21.11 expected, observed/expected ratio (o/e) 0.33, 90% interval 0.19 to 0.62. The upper end of that interval is the gene's LOEUF score, 0.62, which puts it in group 2 of 6, group 1 being the genes least tolerant of losing a copy. Missense variants: 391 observed, 476.76 expected, observed/expected ratio (o/e) 0.82, 90% interval 0.75 to 0.89. Synonymous variants: 179 observed, 188.94 expected, observed/expected ratio (o/e) 0.95, 90% interval 0.84 to 1.07.
Homologues: Orthologues: chimpanzee LPAR3 (99% identical), macaque LPAR3 (97% identical), dog LPAR3 (94% identical), rabbit LPAR3 (94% identical), guinea pig LPAR3 (93% identical), mouse Lpar3 (92% identical), rat Lpar3 (92% identical), pig LPAR3 (86% identical), tropical clawed frog lpar3 (76% identical), zebrafish lpar3 (61% identical). Paralogues in human: LPAR1 (47% identical), LPAR2 (45% identical), S1PR3 (32% identical), S1PR1 (32% identical), S1PR2 (30% identical), S1PR4 (29% identical), S1PR5 (28% identical), GPR3 (24% identical), GPR6 (24% identical), GPR12 (22% identical), CNR1 (22% identical), MC5R (21% identical), and 6 more.
Diseases named in the same sentence as LPAR3 in open-access papers:
LPAR3 is named in the same sentence as 85 diseases in open-access papers, as found by Europe PMC text mining. Sharing a sentence is not in itself a finding about the gene and the disease. The quoted sentences say what the papers report.
ovarian carcinoma (27 papers, 2014 to 2024). A malignant neoplasm originating from the surface ovarian epithelium. "LPAR3/G13 signaling is also implicated in YAP-mediated long-term migration of human ovarian cancer cells." (PMID 34440828, 2021). "LPAR3 has been implicated in ovarian cancer progression and cell migration, but was also reported to inhibit cell migration and invasion in colon cancer cells." (PMID 24928086, 2014). "Other studies found that increased expression of LPAR3 increases malignancy in breast and ovarian cancers in vivo." (PMID 36785669, 2023). "Particularly, LPAR2 and LPAR3 have been shown to be frequently overexpressed in ovarian cancer cells and tissues." (PMID 35625966, 2022). "The level of LPAR3 was upregulated in ovarian cancer cells compared with that in the corresponding normal tissue." (PMID 36088312, 2022). "MiR-15b can repress proliferation, migration, and invasion of ovarian cancer cells by binding to LPAR3 mRNA and inhibiting Bcl-2 and the PI3K/Akt pathway." (PMID 35814375, 2022). "In contrast, LPAR3 is a prognostic factor of ovarian cancer in the Human Protein Atlas, and its high expression is favorable in ovarian cancer." (PMID 34302117, 2021). "Expression of LPAR2 and LPAR3 has been correlated with increased cell aggressiveness in ovarian cancer." (PMID 34440828, 2021). "In ovarian cancer, LPAR3 promotes cell expansion and invasion in SKOV-3 cells, and tumors with overexpression of LPAR3 were associated with poor survival." (PMID 34209775, 2021). "For example, unsaturated LPAs (18:1 LPA and 20:4 LPA) were more potent than saturated LPA (16:0 LPA) in stimulating LPAR3-mediated cell growth in an ovarian cancer cell line (SKOV-3)." (PMID 32547888, 2020). "Strong heterogeneity in LPAR3 mRNA expression levels was detected within a panel of 55 ovarian cancer cell lines." (PMID 31049165, 2019). "With respect to the additional top candidate molecule, LPAR3, we found heterogeneous expression by various cell types within complex ovarian cancer tissue." (PMID 31049165, 2019). "In this exploratory study, we aimed to determine the tumor anatomy-attributed expression pattern of the top 3 candidate molecules – CD68, SMPD1, and LPAR3 – within complex ovarian cancer tissues." (PMID 31049165, 2019). "Some of them are widely expressed in various tissues and therefore we suggest using the LPAR3-specific LPA derivative 1-oleoyl-2-methyl-sn-glycero-3-phosphothionate (OMPT) as ovarian cancer targeting ligand." (PMID 31480803, 2019). "Conversely, ovarian cancer appears to be characterized by decreased LPAR1 expression and tumor aggressiveness is associated with altered LPAR 2 and LPAR3, LPAR3 being capable of signaling via Gi-proteins." (PMID 26701886, 2016). "In human ovarian cancer and rodent hepatoma cells, LPAR3 contributed to tumor-promoting activity." (PMID 36088312, 2022). "However, data on LPAR3 expression in cancer are inconsistent; LPAR3 expression is elevated in ovarian cancer cells." (PMID 36088312, 2022). "For example, LPAR3 acts as a target gene of miR-15b that alleviates tumor growth in ovarian cancer." (PMID 32231464, 2020). "LPAR3 has also been confirmed to be involved in PI3K/AKT pathway in ovarian cancer." (PMID 32231464, 2020). "LPAR3 has been manifested to be tightly related to PI3K/AKT pathway in ovarian cancer." (PMID 32231464, 2020). "Increased expression of LPAR3 was proven to increase malignancy in breast and ovarian cancers." (PMID 32724813, 2020). "The qRT-PCR results showed that LPAR1, LPAR2, and LPAR3 were positive in 75.00 %, 12.50 %, and 6.25 % in the 15 of the normal ovarian specimens, respectively; and 69.23 %, 42.31 %, 17.31 % in the 52 of the ovarian cancer specimens, respectively." (PMID 27809800, 2016). "LPAR3 expression is significantly increased in OC tissue samples compared to normal ovary tissue samples, and this gene might play a role in the carcinogenesis of ovarian cancer." (PMID 35227296, 2022).
ovarian carcinoma (continued). "LPAR2 and LPAR3 might play an role in carcinogenesis of ovarian cancer." (PMID 27809800, 2016). "Direct targeting of LPAR3 by miR-15b has been shown to repress cell proliferation and drive the senescence and apoptosis of ovarian cancer cells through the PI3K/Akt pathway, suggesting the potential mRNA treatment against LPAR3." (PMID 34209775, 2021). "The final selection contained four receptors (GPR39, LPAR3, OXTR and PTH2R) with strong expression in ovarian cancer tissue and generally low expression in human tissues." (PMID 31480803, 2019). "LPARs are overexpressed in ovarian cancer cells and tissues, specifically, LPAR2 and LPAR3." (PMID 40836974, 2024). "Besides Gq and Gi proteins, LPAR3 can also activate G12/13, increase dephosphorylation and nuclear translocation of YAP, and induce migration of ovarian cancer cells." (PMID 34209775, 2021). "However, in our study, we demonstrated that LPAR1 expression in invasive ovarian cancer cells was significantly higher than in non-invasive ones; while the expression of LPAR2 and LPAR3 had no statistical correlation with the metastatic potential of ovarian cancer cells." (PMID 27809800, 2016).
breast carcinoma (18 papers, 2004 to 2024). "The elevated expressions of Lysophosphatidic Acid Receptor 1 and 3 (LPAR1 and LPAR3), two other hub genes in module 2, are associated with poorly differentiated and advanced stages of breast cancer." (PMID 33202602, 2020). "Consistent with our data, LPAR3 expression is increased in human TNBC and is associated with tumor metastatic ability, suggesting its clinical relevance in breast cancer." (PMID 35216080, 2022). "Many groups have reported that expression levels of LPA receptors (LPAR1, LPAR2, and LPAR3) and/or β-arrestins are elevated in advanced stages of breast cancers." (PMID 34440828, 2021). "Expression of human ATX, LPAR1, LPAR2 or LPAR3 in transgenic mice is sufficient to induce late-onset mammary carcinomas." (PMID 31652837, 2019). "In transgenic mouse models, overexpression of each of these individual LPA receptors (LPAR1, LPAR2 and LPAR3) under the control of the mouse mammary tumour virus long terminal repeat (MMTV-LTR) promoter led to the formation of late-onset mammary carcinomas." (PMID 25572802, 2015). "As opposed to LPAR1, we did not observe significant correlations between ZEB1 and LPAR2 or LPAR3 in publicly available breast cancer cell line databases." (PMID 26098771, 2015). "Proliferation and/or motility of cancer cells were promoted after LPA signalling through the LPAR1 in colon, gastric, and breast cancer, LPAR2 in colon and renal cancer, LPAR3 in colon, pancreatic, and breast cancer, LPAR4 in fibrosarcoma, and LPAR6 in hepatic and pancreatic cancer." (PMID 34722305, 2021). "A particularly important study by Liu and colleagues showed that overexpression of LPAR1, LPAR2, or LPAR3 in transgenic mice could induce mammary tumors." (PMID 34440828, 2021). "Moreover, increased expression of LPAR3 and ATX in breast cancer biopsies is associated with tumor aggressiveness." (PMID 31652837, 2019). "In the present study, we did not observe a significant increase or decrease in mRNA expression of LPAR1, LPAR3, and LPAR6 RNA in breast cancer cells after irradiation." (PMID 39338222, 2024). "In pancreatic cancer, YAP promotes cell motility and invasion via LPA receptor 3 (LPAR3), while in mesothelioma and breast cancer cells, YAP mediates the expression of receptor of hyaluronan-mediated motility (RHAMM)." (PMID 34205830, 2021). "It has been reported that breast cancer cells express elevated levels of LPAR1, LPAR2, and LPAR3 and that these LPA receptors are involved in stimulating tumorigenic and metastatic cascades via Wnt, MAPK, and PI3K pathways." (PMID 34440828, 2021). "Indeed, LPAR1 is crucial in bone metastasis of breast carcinoma, LPAR2 promotes colorectal cancer and aggressiveness of ovarian cancer cells, whereas LPAR3 enhances migration of hepatoma cells (and refer therein)." (PMID 31652837, 2019). "Whereas previous studies found that TNBC cell lines like MDA-MB-231 express the highest levels of LPAR3 within several breast cancer subtypes 14,15, expression of LPAR3 by MDA-MB-231 could not be detected in other studies." (PMID 35365723, 2022).
pancreatic cancer (9 papers, 2015 to 2023). "In addition to our finding that PCa patients in the high LPAR5 expression group had worse survival, other LPAR subtypes were associated with poor survival such as LPAR1 in melanoma, LPAR2 in adrenocortical carcinoma, LPAR3 in pancreatic cancer, and LPAR4 in renal papillary carcinoma." (PMID 36806315, 2023). "For example, LPAR5 is mainly expressed in stomach, colon and pancreatic cancer, while LPAR3 and LPAR4 are predominantly expressed in pancreatic cancer." (PMID 37550785, 2023). "Long-term culturing of PANC-1 cells in the presence of cisplatin resulted in increased expression of LPAR3, suggesting the role of LPA3 in drug resistance in pancreatic cancer." (PMID 31323936, 2019). "YAP was also found to promote pancreatic cancer cell motility, invasion, and tumorigenesis through LPA Receptor 3 (LPAR3), and TAZ-TEAD-dependent expression of Bone Morphogenic Protein 4 (BMP4) promotes mammary cell migration." (PMID 29642615, 2018). "There appears a strong correlation between LPAR3 expression and the triple receptor-negative breast cancers, and LPAR3 knockdown attenuate motility and invasion of breast and pancreatic cancer cells." (PMID 31323936, 2019). "In addition, LPAR3 has also been reported to play a role in embryo implantation and spacing in mice, mediate chemotaxis of immature murine dendritic cells to unsaturated LPA, regulate cellular functions during tumor progression in pancreatic cancer cells, and modulate the aging process." (PMID 32325720, 2020).
melanoma (7 papers, 2010 to 2025). A malignant, usually aggressive tumor composed of atypical, neoplastic melanocytes. "In melanoma, LPAR3 is essential to promote viability and proliferation, and the Src homology 3 domain is required for LPAR3 to mediate viability in melanoma SK-MEL-2 cells." (PMID 34209775, 2021). "LPAR3 has been characterized as the major promoter of long-term viability in melanoma cells." (PMID 36785669, 2023). "Lysophosphatidic acid receptor 3 (LPAR3) is the receptor of LPA and has been reported as a regulator in some diseases, such as melanoma." (PMID 32231464, 2020). "First, we analyzed the relative expression levels of various LPA receptors in human A375 and A2058 melanoma cells as representatives of primary and metastatic melanoma models, respectively, and found that both cell lines expressed predominantly LPAR1 and LPAR3." (PMID 39187677, 2025).
prostate carcinoma (7 papers, 2012 to 2023). A carcinoma that arises from epithelial cells of the prostate gland. "Recent bioinformatics analysis has shown that LPAR3 is one of the hub genes in high-grade prostate cancer." (PMID 32724813, 2020).
colon cancer (6 papers, 2014 to 2022). "LPA increases the expression of KLF5 to increase cell proliferation in colon cancer cells, and this LPA-induced KLF5 expression is mediated by LPAR2 and LPAR3." (PMID 36142408, 2022).
hepatocellular carcinoma (6 papers, 2016 to 2022). A malignant tumor that arises from hepatocytes. "Another article indicated that LPAR3 conferred chemo-resistance by upregulating multidrug resistance-related genes because the cell survival in LPAR3-expressing rat hepatoma cells treated with cisplatin or doxorubicin was higher than controls." (PMID 34209775, 2021). "LPAR3-expressing cells were created from murine hepatoma cells and compared with LPAR3-unexpressing cells, regarding their migration and tumorigenicity abilities." (PMID 28402936, 2017). "The LPAR1/LPAR3 expression is increased in hepatoma cell line SKHep1, and the LPA-LPAR3 signaling may play an essential role in tumor invasiveness/expansion." (PMID 30705088, 2019). "In this study we report the microenvironment in human hepatocellular carcinoma (HCC) and non-tumor liver (NTL) is characterized by a subset of cells expressing LPAR1 and LPAR3, a profile shared by the human hepatic tumor-derived SKHep1 cell line." (PMID 26701886, 2016).
liver cancer (6 papers, 2016 to 2022). An epithelial or non-epithelial malignant neoplasm that arises from the liver. "circRNA LPAR3 can promote the development of liver cancer by promoting the invasion, migration, and metastasis of esophageal cancer cells." (PMID 35646112, 2022). "Using antibodies against CD44 and EpCAM1 (markers of mesenchymal stem cells and liver cancer progenitor cells) we identified cells expressing LPAR3 in the HCC-NTL margin also expressed these stem cell markers." (PMID 26701886, 2016). "The migration ability of SKHep1 cells can be enhanced by LPA3-Gαi-ERK-MAPK signaling pathway, indicating that LPAR3 can promote the development of liver cancer." (PMID 32284748, 2020).
endometriosis (5 papers, 2012 to 2024). The growth of functional endometrial tissue in anatomic sites outside the uterine body. "Interestingly, in our mouse endometriosis model, endometrial tissues from Lpar3 KO mice were significantly less developed." (PMID 28588064, 2017).
thyroid cancer (5 papers, 2019 to 2023). "LPAR3 was reported as a part of the ZEB1-AS1/miR-133a-3p/LPAR3/EGFR axis that promotes thyroid cancer progression by regulating PI3K/Akt/mTOR signaling." (PMID 32724813, 2020). "Lysophosphatidic acid receptor 3 (LPAR3) and epidermal growth factor receptor (EGFR) were direct targets of miR-133a-3p in thyroid cancer." (PMID 35314614, 2022). "Furthermore, miR‐133a‐3p can regulate the PI3K/AKT/mTOR signaling pathway in thyroid cancer by modulating ZEB1‐AS1 and targeting LPAR3 and EGFR, inhibiting thyroid cancer cell proliferation while promoting cell death." (PMID 36305754, 2023).
anemia (3 papers, 2020 to 2024). A reduction in the number of red blood cells, the amount of hemoglobin, and/or the volume of packed red blood cells. "Our previous research demonstrated that lysophosphatidic acid receptor 3 (LPA3) activation mitigated oxidative stress in progeria cells and accelerated the recovery of acute anemia in mice." (PMID 38397002, 2024).
bladder cancer (3 papers, 2019 to 2023). "Of these, three hub genes involving angiotensin II receptor, type 2 (AGTR2), fibroblast growth factor 13 (FGF13), and lysophosphatidic acid (LPA) receptor 3 (LPAR3) (marked by red color) have been reported to participate in cell migration and angiogenesis in bladder cancer or lactotroph tumors." (PMID 31708963, 2019).
esophageal cancer (3 papers, 2021 to 2023). A primary or metastatic malignant neoplasm involving the esophagus. "Circular RNA LPAR3 sponges microRNA-198 to facilitate esophageal cancer migration, invasion, and metastasis." (PMID 35646112, 2022). "CircRNA LPAR3 could interact with miR-198/MET axis to enhance the metastatic capacity of esophageal cancer cells." (PMID 37020694, 2023).
gastric cancer (3 papers, 2013 to 2022). A primary or metastatic malignant neoplasm involving the stomach. "Data from another study have shown that LPAR-1, LPAR-2, and LPAR-3 are present in gastric cancer cell lines; among them, LPAR2 was expressed aberrantly in the AGS cell line." (PMID 36551233, 2022). "To identify the LPAR(s) involved in LPA-induced EGFR transactivation in gastric cancer, we evaluated the mRNA levels of various LPARs by qRT-PCR and found that LPAR3 was more highly expressed than the others." (PMID 34658851, 2021). "Given our observation, LPA stabilized geminin via the LPAR3/MMPs/EGFR/PI3K/mTOR signaling axis in gastric cancer cells, we examined whether this pathway modulated cell-cycle progression." (PMID 34658851, 2021). "Thus, LPA promotes S-phase cell-cycle progression in gastric cancer cells via the LPAR3/MMPs/EGFR/PI3K/mTOR signaling axis." (PMID 34658851, 2021). "Thus, LPA enhances geminin stability via the LPAR3/MMPs/EGFR/PI3K/mTOR signaling axis in gastric cancer." (PMID 34658851, 2021). "To confirm the role of LPAR3 in LPA-meditated geminin upregulation, we evaluated geminin protein levels in gastric cancer cells treated with the LPAR1/3 inhibitor Ki16425 by Western blotting." (PMID 34658851, 2021). "Knockdown of LPAR3 reduced the protein level of geminin that was increased by LPA treatment, whereas no change in geminin expression was observed in gastric cancer cells that were transfected with a control siRNA (sitrl) or siLPAR3 in the absence of LPA." (PMID 34658851, 2021). "LPAR2 was observed to be highly expressed in SGC-7901 cells, a human gastric cancer cell line, while LPAR1 and LPAR3 were not." (PMID 23426604, 2013).